NKX2-1 (NK2 homeobox 1)
Diseases named in the same sentence as NKX2-1 in open-access papers (continued):
Sharing a sentence is not in itself a finding about the gene and the disease.
lung carcinoma (continued). "Several studies focusing on the role of NKX2-1 in lung cancer prognosis have already been examined." (PMID 33086649, 2020). "We identified at least five proteins of interest (NKX2-1, CAV1, YBX1, FN1 and CDH3) with two different machine learning models that may be associated with lung cancer patient survival." (PMID 33086649, 2020). "It has been previously suggested that TBX5, SPRED, and NKX2-1 may function as tumor suppressors in lung cancer, while nothing is known about the function of GMIP in any human cancer." (PMID 33227088, 2020). "The NKX2–1 locus, which encodes TTF-1, is frequently amplified in the lung cancer genome." (PMID 31196060, 2019). "Thus, NKX2-1, FoxA1 and FoxA2 coordinately regulate the growth and identity of lung cancer in a context-specific manner." (PMID 30475207, 2018). "In this context, NKX2–1 has a role as lineage-survival oncogene in developing lung cancer tumors." (PMID 30217225, 2018). "We hypothesized that miR-365a, NKX2–1 and miR-33a could work together to influence growth and differentiation of lung cancer cells and that the study of this axis could thus help to understand the discrepancies observed in the prognostic impact of NKX2–1." (PMID 29237428, 2017). "In addition, of the genes involved in other cancers, 2/8 are related to gemcitabine: TGIF-1 modifies gemcitabine resistance in bladder cancer, and NKX2-1 higher expression increases gemcitabine cytotoxicity in lung cancer cells." (PMID 29023490, 2017). "Indeed, in some contexts (mainly in the mouse), Nkx2-1 seems to function more as a tumor suppressor, inhibiting Kras-driven lung cancer and lung cancer metastasis." (PMID 26556242, 2015). "In particular, Nkx2-1 was recently shown to be required for Egfr-driven murine lung cancer." (PMID 26556242, 2015). "Other prominent examples include MITF in melanoma and NKX2-1 (TTF1) in lung cancer." (PMID 24040285, 2013). "We evaluated a three-protein signature consisting of a physiological protein (MUC1), a cancer-specific protein (HIF1A), and a lineage-specific protein (NKX2-1) that could discriminate lung cancer and its major subtypes with a low failure rate." (PMID 23028920, 2012). "The transcriptional program directly controlled by Nkx2-1 in early and late mouse lung development that may explain its primary developmental effects, and the genes regulated by NKX2-1 in human lung cancer are unknown." (PMID 22242187, 2012). "HIF1A and NKX2-1 classified the major subtypes of lung cancer with a failure rate of 8.4%." (PMID 23028920, 2012). "In conclusion, this study presents the first comprehensive review of respiratory manifestations in patients with NKX2-1-RD, shedding light on the diverse clinical spectrum from neonatal respiratory distress to severe lung diseases, such as interstitial lung disease and lung cancer." (PMID 40395234, 2025). "Respiratory manifestations linked to NKX2-1-RD encompass a broad spectrum, including interstitial lung disease (ILD), neonatal respiratory distress syndrome (RDS), recurrent infections, chronic respiratory insufficiency, pulmonary hypertension, asthma, and lung cancer." (PMID 40395234, 2025). "For example, NKX2-1 is considered a tumor suppressor in lung cancer—a function perhaps attributable to its role in limiting cellular potentials such that the increased epigenetic plasticity of NKX2-1 mutant tumor cells may allow adaptation and growth advantage in the tumor microenvironment." (PMID 33947861, 2021). "In lung cancers, NKX2-1 is amplified and may participate in the pulmonary tumorigenic process." (PMID 26871466, 2016).
lung carcinoma (continued). "In addition to genes associated with smoking the AC1/AC2 classifier included several genes implicated in lung cancer tumorigenesis, such as KITID1MMP7MYCNXRN2, and CYP24A1, as well as type II pneumocyte marker genes such as NKX2-1 (TTF1/TITF1), LAMP3 (CD208), and surfactant proteins SFTPB and SFTPC." (PMID 22676229, 2012). "Our results may also have important implications for understanding NKX2-1 functions in lung cancer." (PMID 22242187, 2012). "Previous studies have revealed that the expression of the NKX homeobox-1 (NKX2-1) gene, also referred to as thyroid transcription factor-1 (TTF-1), is a specific biomarker of lung carcinomas." (PMID 41415280, 2025). "Nkx2-1 and Foxa2 are co-expressed in normal AT2 cells and they can also coordinately regulate lung cancer cell growth and identity in a context-specific manner." (PMID 36993454, 2023). "NKX2–1 overexpressing and NKX2–1 knockdown/knockout T-cell leukaemia and lung cancer cell line models were established to study metabolic rewiring using ChIP-qPCR, immunoblotting, mass spectrometry, and proliferation and invasion assays." (PMID 36932191, 2023). "miR-365 can interact with TTF-1 or NK2 homeobox 1 (NKX2-1) and the 3′-UTR of high mobility group AT-hook (HMGA2) to inhibit EMT in lung cancer cells." (PMID 35805066, 2022). "Parallel evolution has been shown in a variety of neoplasms, including lung cancers involving genetic alterations in the MUC1, CDK4, CHD8, and NKX2‐1 genes." (PMID 32333643, 2020). "NKX2-1 also acts as an activator of HOP (Hsp70/Hsp90 Organizing Protein), a potential tumor suppressor gene in lung cancer, inhibiting epithelial to mesenchymal transition." (PMID 32925947, 2020). "The individual functions of NKX2-1, miR-200c, MYB, and NFIB in lung development and/or lung cancer have been widely documented." (PMID 25763778, 2015). "Moreover, lung cancer patients with elevated expression of TCF21, NKX2-1, TBX2, and TBX5 exhibited a decreased rate of survival relative to patients with low gene expression." (PMID 37627195, 2023). "FoxA1/2, another lineage-specifying transcription factor, drives gastric differentiation and suppresses squamous identity in NKX2-1-negative lung cancer." (PMID 38093367, 2023). "This region containing NKX2-1 and NKX2-8 genes were reported as prognostic factors in lung cancer." (PMID 35402275, 2022). "Furthermore, IPA upstream analysis predicted the activation or inhibition state of many important transcription factors that were previously reported to be involved in the pathogenesis of lung cancer such as FOXM1, NRF2, TP63, NKX2-1, and ATF3 18,36–39." (PMID 31444368, 2019). "The precise mechanisms by which FoxA1/2 specifically activate a gastric program in NKX2-1 negative lung cancer, as opposed to other potential endodermal differentiation states (e.g. hepatic, pancreatic, lower GI tract etc.), remain to be determined." (PMID 30475207, 2018). "Previously, our ChIP‐seq analyses determined that NKX2‐1 and FOXA3 bound to the locus of MUC5AC in A549 lung carcinoma cells and BEAS‐2B transformed bronchial epithelial cells, suggesting that the expression of MUC5AC is directly regulated by NKX2‐1 and FOXA3." (PMID 28255028, 2017). "In lung cancer, NKX2-1 has been proposed as a positive or negative prognostic factor depending on expression levels." (PMID 22242187, 2012). "Investigation of microarray data from the Cancer Cell Line Encyclopedia (CCLE) showed that the median values of NKX2‐1 expression in lung cancers were higher among cancers originating from different tissues, and SCLC showed significantly higher expression than other types of lung cancers." (PMID 31782890, 2020). "Reverse transcriptase-polymerase chain reaction (RT-PCR) was used to identify the presence of mRNA for NKX2-1, also known as TTF-1, a marker of lung differentiation, and eleven receptor and cytoplasmic tyrosine and serine/threonine kinases, in the BACA and CLAC canine lung cancer lines." (PMID 26560147, 2015).
lung carcinoma (continued). "However, while HOPX expression is activated by NKX2-1 in lung cancer cells, it was not regulated by NKX2-1 in SU-DHL-5 cells." (PMID 23637834, 2013). "Conversely, some reports showed that NKX2-1 may suppress lung adenocarcinoma progression via impeding TGF-β-induced epithelial-to mesenchymal transition (EMT) due to increased E-cadherin expression and occuludin targeted by NKX2-1 impeded migration and induced aknoikis in lung cancer cells." (PMID 25881545, 2015).
lung adenocarcinoma (119 papers, 2003 to 2026). A carcinoma that arises from the lung and is characterized by the presence of malignant glandular epithelial cells. "Downregulation of NKX2‐1 is known to be associated with poorly differentiated lung adenocarcinoma (LUAD) tumors exhibiting high metastatic potential." (PMID 39113226, 2024). "An association between EGFR mutations and NKX2-1 expression has been described in lung adenocarcinoma." (PMID 37111634, 2023). "In 2023, Ebisudani tested C59, a novel porcupine inhibitor, for Wnt-targeted therapeutic efficacy in an NKX2-1-deficient lung adenocarcinoma chip." (PMID 38026900, 2023). "We identified NKX2-1 as a transcriptional regulator inactivated in lung adenocarcinoma, linked to a large number of enhancers silenced in cancer." (PMID 32925947, 2020). "Among the identified transcriptional regulators inactivated in lung adenocarcinoma vs. normal lung, NKX2-1 was linked to a large number of silenced enhancers." (PMID 32925947, 2020). "In previous work, we and others have shown that loss of NKX2-1 is sufficient to cause lineage switching in a mouse model of KRASG12D-driven lung adenocarcinoma." (PMID 30475207, 2018). "Loss of the pulmonary lineage specifier NKX2-1 augments the growth of KRAS-driven lung adenocarcinoma and causes pulmonary to gastric transdifferentiation." (PMID 30475207, 2018). "FoxA1 and FoxA2 are required for initiation and proliferation of NKX2-1-deficient lung adenocarcinoma." (PMID 30475207, 2018). "We have previously shown that engineered loss of the pulmonary lineage specifier NKX2-1 causes lung adenocarcinoma cells to shed their pulmonary identity and adopt a gastric differentiation state that is also observed in human IMA." (PMID 30475207, 2018). "In lung adenocarcinoma a high-level of NKX2-1 expression is significantly associated with longer overall survival, whereas a high-level of miR-200c expression is associated with shorter overall survival supporting the inverse correlation." (PMID 25763778, 2015). "Knockdown of NKX2-1 causes suppression of cancer cell proliferation and, as a result, may be used as a molecular target in the treatment of lung adenocarcinoma." (PMID 38916623, 2024). "Importantly, loss-of-function mutations or silencing of NKX2-1 is a relatively infrequent event in lung adenocarcinoma." (PMID 31452510, 2019). "We examined the possibility that NKX2-1 expression could be associated with IKKβ expression in 157 tumours from lung adenocarcinoma patients." (PMID 25881545, 2015). "Indeed, these findings bear similarity to observations in human lung adenocarcinomas in which poorly differentiated and metastatic cancers often show loss of expression of functional markers of lung identity despite maintaining expression of NKX2-1." (PMID 31452510, 2019). "To test the hypothesis that FoxA1/2 are required for lung adenocarcinoma cells to undergo a pulmonary to gastric lineage switch upon loss of NKX2-1 expression, we incorporated conditional alleles of Foxa1 and Foxa2 into a mouse model of NKX2-1-deficient lung adenocarcinoma." (PMID 30475207, 2018). "Organoid screening demonstrated that NKX2‐1 expression status determines Wnt dependency and predicts therapeutic response to Wnt‐targeting therapy in lung adenocarcinoma." (PMID 41503026, 2026). "uncovered that NKX2‐1 expression delineates Wingless‐related integration site (Wnt)‐dependent from Wnt‐independent states in lung adenocarcinoma, offering an NKX2‐1‐guided stratification framework to forecast the efficacy of Wnt‐directed therapies." (PMID 41503026, 2026).
lung adenocarcinoma (continued). "In lung adenocarcinoma, NKX2-1 (TTF-1) gain at 14q13.3 acts as a lineage-survival oncogene essential for tumor growth, but evidence does not support a direct relationship with immune checkpoint inhibitor response." (PMID 41303594, 2025). "A recent study showed that NKX2-1 is expressed in certain types of lung adenocarcinoma resulting in unfavorable prognosis." (PMID 38916623, 2024). "NK2 Homeobox 1 (NKX2‐1) is a well‐characterized pathological marker that delineates lung adenocarcinoma (LUAD) progression." (PMID 39113226, 2024). "NKX2-1 serves as a marker for LPC differentiation; however, it is also associated with cancer, particularly in lung adenocarcinoma where it is highly expressed." (PMID 38132167, 2023). "For example, a homeobox transcription factor NKX2-1 was found to be involved in both the development and metastasis of lung adenocarcinoma and the activation of CCND1 through interacting with its promotor." (PMID 35365622, 2022). "SELENBP1 was demonstrated to be involved in the tumor growth-suppressive effects of Nkx2-1, and it was reported to inhibit tumor growth and the migration of lung adenocarcinoma." (PMID 35205284, 2022). "NKX2-1 is expressed in 70% of lung adenocarcinomas and can act either as an oncogene or tumor suppressor." (PMID 35081981, 2022). "We therefore used a dual recombinase system in the present study to assess the role of NKX2-1 in the established BRAFV600E lung adenocarcinomas." (PMID 33821796, 2021). "In murine BRAFV600E-driven lung adenocarcinoma, NKX2-1 is required for early tumorigenesis, but dispensable for established tumor growth." (PMID 33821796, 2021). "To dissect the role of NKX2-1 in mutant BRAF-induced lung adenocarcinoma, we utilized two established mouse strains bearing recombinase-activatable alleles of BrafV600E." (PMID 33821796, 2021). "We have previously shown that Nkx2-1 deletion augments ERK activity in KRASG12D-driven lung adenocarcinoma, and feedback inhibition of the MAPK pathway is known to be rate-limiting for the growth of KRASG12D-driven tumors in vivo." (PMID 33821796, 2021). "Nkx2-1 deletion induces mucinous adenocarcinoma but impairs tumor initiation in BRAFV600E-driven lung adenocarcinoma." (PMID 33821796, 2021). "NKX2-1 has been used as a molecular marker for lung adenocarcinoma in clinical work, especially for diagnosis of metastatic sites." (PMID 32929382, 2020). "Clinical studies showed that low NKX2-1 level correlated with unfavorable prognoses in lung adenocarcinoma patients." (PMID 33542901, 2020). "Thyroid transcription factor‐1 (TTF‐1, encoded by the NKX2‐1 gene) is highly expressed in small‐cell lung carcinoma (SCLC) and lung adenocarcinoma (LADC), but how its functional roles differ between SCLC and LADC remains to be elucidated." (PMID 31782890, 2020). "Here, we considered two additional scenarios, namely NKX2-1 in lung adenocarcinoma and SOX2 in squamous cell carcinomas." (PMID 31050342, 2019). "Gratifyingly, quantitative PCR indeed uncovered a notable reduction of NKX2-1 or SOX2 levels along with HDAC blockage in all tested lung adenocarcinoma or squamous cell carcinoma models, respectively." (PMID 31050342, 2019). "SAE-enriched transcription factor, NKX2–1, is relevant to lung adenocarcinoma, a cancer type that is derived from the small airway epithelium." (PMID 31443657, 2019). "The protein most directly demonstrated to influence both lung adenocarcinoma differentiation status and progression is NKX2-1, a homeodomain transcription factor." (PMID 31452510, 2019). "Other therapeutic targets included NTRK1 and NKX2-1, both of which were discovered as targetable oncogenes and promising results in lung adenocarcinoma have been reported." (PMID 30018380, 2018).